CD4 (CD4 molecule)
Diseases named in the same sentence as CD4 in open-access papers (continued):
Sharing a sentence is not in itself a finding about the gene and the disease.
cancer (continued). "Olsenella species have been shown to enhance the efficacy of anti‐CTLA‐4 treatment and boost the activation of CD4+ and CD8+ T cells in four mouse models of cancer." (PMID 40351363, 2025). "Stratified randomization by baseline CD4 count, HIV viral load, and cancer type would significantly improve the statistical rigor of future studies assessing ICI safety and efficacy in PHIV." (PMID 40863204, 2025). "In exploring the role of GTF2E2, a gene associated with immune regulation, we found that its expression correlates positively with the presence of CD4+ and CD8+ T cells across various cancers." (PMID 40267151, 2025). "Inducing both CD4+ and CD8+ responses would be expected to result in a more pronounced anti-cancer immune response compared to only a CD4+ or CD8+ T cell response." (PMID 40573960, 2025). "High NAD(P)H autofluorescence was emitted by cancer cells and immunoactive cells including dendritic cells (CD11c+), M1 macrophages (F4/80+MCP1+CCR2+), and Th cells (CD4+)." (PMID 40112892, 2025). "This shift indicates that activated CD8+ T cells effectively attacked cancer cells in the TME, which was supported by an increased number and activation of CD4+ and CD8+ T cells in the spleen." (PMID 40343532, 2025). "This was closely associated with an increased infiltration of CD3+ T cells, both CD4+ and CD8+, in the cancer stage in comparison with WT mice." (PMID 40087977, 2025). "Two authors (FM, VP) independently extracted data, including study characteristics, patient demographics, cancer stage, treatment details, outcomes, toxicities, and HIV-related data (CD4 counts, viral load, ART regimens)." (PMID 41573453, 2025). "Correlations between LUC and CD8+ as well as CD4 + T cells were also noted in HIV patients and LUC was suggested to be a predictive biomarker for hematologic toxicities in cancer and hematologic malignancies." (PMID 40910405, 2025). "This leads to increased numbers of CD4+IFNγ+, CD8+IFNγ+, and CD11b+F4/80+ immune cells in the tumors, ultimately helping to destroy cancer cells." (PMID 40006729, 2025). "Testicular cancer patients show specific immune responses to cancer/testis antigens via CD8+ and CD4+ T cells, which diminish post-treatment." (PMID 40260236, 2025). "Similar to the cancer cells, single-cell sequencing showed that individual CTA genes were activated only in a small subset of CD4 + T cells and individual CD4 + T cells expressed seemingly random subsets of the CTA genes in the DNMTi-treated cell population." (PMID 39844304, 2025). "Hence, while pomalidomide is described as pro-apoptotic through caspase-8 upregulation and inhibiting IAP-2 in cancer cell lines, in this study, we observed that pomalidomide treatment paradoxically supported cell survival through upregulating Bcl-2, improving the viability of CD4+ T cells." (PMID 39902962, 2025). "The study also identified several risk factors for the development of severe irAEs, including low CD4+ T-cell count, longer duration since HIV diagnosis, history of cancer surgery, and positive cytomegalovirus serology at the initiation of ICI therapy." (PMID 40647389, 2025). "A total of 9 cell types were annotated, including macrophages, T cells (CD4 + and CD8 +), dendritic cells (DC), natural killer cells (NK cells), B cells, Fibroblast/Stromal cells and cancer cells." (PMID 40280979, 2025). "Tregs, another subset of CD4+ T-cells, mainly prevent autoimmunity but, in the TME, promote cancer progression by suppressing effector T-cells and fostering an immunosuppressive environment." (PMID 40260236, 2025). "CD4 T cell infiltration triggers the activation of CD8 T cells, promoting apoptosis and cytotoxic activity against cancer cells." (PMID 39963108, 2025). "SMAC mimetics, such as LCL-161 (SM-406), AT-406 (Debio-1143), and BP, known as therapeutic agents for cancers, induce autophagy-dependent apoptosis of HIV-1-infected macrophages and resting memory CD4+ T cells." (PMID 40392781, 2025).
cancer (continued). "The lung metastases were infiltrated with CD4+ and CD4+CD8+ double-positive T cells and presented a significant improvement in immune responses to cancer compared to controls." (PMID 40092697, 2025). "The ex vivo mEp-NIR-PIT effectively eliminated nearly all the cancer cells within TME, whereas CD8 and CD4 T cells, DCs, and endothelial cells (ECs) remained unaffected." (PMID 40792441, 2025). "Because of the limitations of the study design, we recommend a prospective study to further determine the prevalence of cancer among PLHIV and the interaction with the different ART regimens, CD4 cell count and viral load." (PMID 39869644, 2025). "In contrast, Cycling GZMA CD4 T cells expressed GZMA and demonstrated a marked upregulation of anti-cancer-related genes, including IFNG, PRF1, and TNFSF10." (PMID 40959273, 2025). "MARCH8 expression was significantly related to CD4+ T memory resting cells, B naive cells, and macrophages in most cancers, which proved the potential immune function of MARCH8 across cancer types." (PMID 39881438, 2025). "By using a monoclonal antibody approach for CD4+ T cell depletion, our data further confirm the importance of MHC-II neoepitopes in shaping antitumor immunity elicited by cancer vaccine." (PMID 39888994, 2025). "These responses are supported by robust CD4+ and CD8+ T-cell immunity, with CD4+ T-cells coordinating the immune response and CD8+ T-cells attacking and eliminating cancer cells." (PMID 40075668, 2025). "In contrast, enhanced clonality was evident for CD4+ CXCL13+ Tfh cells and CD8+ CXCL13+ T cells in ICB-Rs, showing distinctive TCR dynamics at play in the ICB response to cancer." (PMID 40054456, 2025). "Specifically, the fractions of CD4+ T cell and CD8+ T cell infiltration showed consistent increasing and decreasing trends in 14 cancer types compared with normal tissues." (PMID 40004489, 2025). "Niche 4 contained predominantly CK+ carcinoma cells, while niche 5 showed an abundance of CD3+ and CD4+ cells." (PMID 41184299, 2025). "Espinosa-Carrasco group demonstrated that CD4+ T cells must engage with CD8+ T cells and DCs, forming a three-cell-type cluster, be able to eliminate cancer cells." (PMID 39582060, 2024). "Immunotherapies that focus on CD4+ and CD8+ T cells have shown great potential in treating various cancers, including bladder cancer 3-5." (PMID 39479459, 2024). "We also evaluated the percentages of CD4 and CD8 T cells, the latter of which showed a significant increase in the cancer groups." (PMID 39317690, 2024). "For each cancer types, the threshold values of CD3/CD4/CD8 will change due to the density scores based on each T-cell biomarker." (PMID 38146436, 2024). "Our study suggests that C + D therapy promotes the infiltration of CD4+ and CD8+ CTLs and elevates the ratio of CD8+ T cells to FOXP3+ Tregs, eliciting local anti-cancer immunity in TME and resulting in prolonged survival outcomes." (PMID 39090653, 2024). "Collectively, we observed decrease of TEMRA CD4+ and CD8+ T-cell subsets in advanced cancer, similar to our transcriptomic data." (PMID 38719807, 2024). "The reduction in immune cells and CD4+/CD8+ ratio are closely related to postoperative recovery and cancer metastasis." (PMID 38968483, 2024). "M2 macrophages (M2MAC), CD4+ follicular helper (TFH), T-17 helper (TH17), and CD8+ terminally exhausted cells (CD8TEREX) were observed to be specifically enriched in cancers when compared to benign and healthy tissues." (PMID 38645221, 2024). "The adaptive immune system, including CD4+ helper T cells and CD8+ cytotoxic T cells, plays a crucial role in fighting cancer." (PMID 38923962, 2024). "This design drastically improved antigen-specific CD4+ and CD8+ T cell induction and anti-cancer effect compared to the injection of antigen mRNA alone in a naked form after intranodal injection." (PMID 38528828, 2024).
cancer (continued). "For function, we also found that even though CD4+T cells have higher cytotoxicity than CD8+T cells towards HCC, blockade of CD8 also improved cancer cell progression in Bcl6 KO group." (PMID 38956432, 2024). "Treg cells represented the main IL23R-expressing cancer T cell cluster, accounting for over 50% of the IL23R+CD4+ T cells and 29% of total IL23R+ pan-cancer T cells." (PMID 38356059, 2024). "In vivo deletion of T lymphocyte subsets including CD4+ and CD8+ T cells reversed the OMV-PP-induced repression of cancer growth." (PMID 38166929, 2024). "We examined the percentages of CD3+, CD3+CD4+, CD3+CD8+, CD14+, and CD3-CD16+CD56+ cells in PBMC samples from 520 cancer patients and 109 healthy individuals, as well as the factors that affected them." (PMID 38911366, 2024). "The study examined 97 patients and found that in WHO/ISUP grades 3–4, CD4 and CD8 T cells were upregulated within cancer cells, while cytokine production was significantly lower." (PMID 38413653, 2024). "T helper (CD4+) and T cytotoxic (CD8+) cell subset compositions in cancer patients differ from those in healthy individuals, with potential influences on the effectiveness of CAR T cell products." (PMID 38473878, 2024). "To explore whether HIV-1 can induce centrosome abnormalities, we performed immunostaining analyses with primary CD4+ T cells purified from the PBMCs of 14 healthy individuals and 10 individuals living with HIV-1 (before they developed HIV-1-associated disorders, including cancer)." (PMID 38443376, 2024). "We suggest that these modified CD4+ T cell-derived exosomes can serve as novel activators of CD8+ T cells, offering a new approach to amplify antitumor efficacy in cancer immunotherapy." (PMID 38172594, 2024). "Another study in this review found that women with cancer and HIV-infection with lower CD4 cell counts had shorter survival when compared with their HIV-negative counterparts." (PMID 38549952, 2024). "After extracting and annotating the marker genes of different T cell subgroups, it was observed that the subgroups of CD4 and CD8 cells in cancer patients were significantly elevated." (PMID 38434988, 2024). "NeoVax is a vaccine of up to 20 predicted individual tumor neoantigens inducing multifunctional CD4+ and CD8+ T cells to target 60% and 16% of new neoantigens observed in patients with cancers, respectively." (PMID 39409876, 2024). "In ESCC, naïve CD4+ T cells, exhausted CD8+ T cells, and NK cells were mainly enriched in the cancer areas of the metastatic sample." (PMID 39858416, 2024). "These probiotics have demonstrated potential in enhancing anti-cancer immunity by reducing Treg levels, promoting CD8+ T-cell activation and CD4+ T-cell differentiation, and facilitating intratumoral NK cell infiltration 279,280." (PMID 38617537, 2024). "The density of CD4+ T cells and CD20+ B cells were lower in cancer tissues than in paracancerous tissues (P < 0.001 and P < 0.001, respectively)." (PMID 38617839, 2024). "It is essential to optimize the delivery of CD4+ and CD8 T-cell epitope ratios and the combinatorial protocol to maximize the potential of cancer vaccines." (PMID 39092051, 2024). "The immune cells of the TME, mainly CD4+ and CD8+ TILs, suppress the proliferation of cancer cells and play a crucial role in cancer progression." (PMID 38779258, 2024). "Overall, the infiltration levels of CD4+ Tcm cells, CD4+ T cells, and NK cells and neutrophils were negatively correlated with CLDN18.2 expression in most cancers, whereas the results for other immune cells were cancer-specific." (PMID 39555091, 2024). "Low CD4 count, positive CMV serology, history of cancer surgery and a longer time since HIV diagnosis were associated with the occurrence of severe irAEs." (PMID 39513741, 2024).
cancer (continued). "Furthermore, naive CD4 T cells may also play a crucial role in triggering and regulating the immune response against cancer, by orchestrating various immune mechanisms to identify, respond to, and potentially eradicate cancer cells." (PMID 38538696, 2024). "Although the importance of CD4+ T cells and MHC class II–restricted neoepitopes in cancer vaccine efficacy has been previously reported, our current findings do not support a major role for them in mediating the antitumor effects of the LPP-mRNA vaccines." (PMID 39392882, 2024). "Two extensively studied cell populations in immuno-oncology are the CD4+ Treg and CD8+ Tex cells as their immunosuppressive functions largely contribute to cancer cells escape from immunosurveillance." (PMID 39729479, 2024). "Enhancing the adaptive immune system to fight cancer, including B lymphocytes, CD4+ helper T lymphocytes, and CD8+ cytotoxic T lymphocytes, is a promising therapeutic strategy for cancer." (PMID 38923962, 2024). "CD4 + Th1 cells, stimulated by IL-12, IFN-γ, and IL-2, secrete pro-inflammatory cytokines, and have anti-cancer effects." (PMID 37505298, 2024). "Positive associations were detected between peripheral PD-1+CD4+ T cells and PD-1+CD4+, PD-1+Cd8+, and CD39+CD8+ T cells in cancer tissue, and between CD39+CD4+ and CD39+D8+ T cells in peripheral and cancer tissue." (PMID 39735530, 2024). "In various of cancers, P4HA3 expression was positively correlated with infiltrated central memory CD8+ T cell, central memory CD4+ T cell, Type 1 T helper cell, regulatory T cell, natural killer cell, macrophage and mast cell." (PMID 39504328, 2024). "Further combining the results of ESCA and PAAD revealed that the infiltration patterns of the CD4+ T cell subsets were similar between the high- and low-CLDN18.2 expression groups across the three cancers, as were those of CD8+ T cell subsets." (PMID 39555091, 2024). "Flow cytometry was used to determine the number of T cells (including CD4 and CD8 subsets), NK cells, and monocytes in PBMC samples from 520 cancer patients and 109 healthy people." (PMID 38911366, 2024). "Previous studies indicated that cancer cells are able to suppress the cytotoxic functions of CD8+ T cells by recruiting Tregs, MDSCs, and CD4+ T cells." (PMID 38510750, 2024). "Regulatory T cells exert inhibitory effects on the anti-cancer functions of CD8+ T cells, as well as CD4+ T cells and dendritic cells (DCs) that facilitate the activation of CD8+ T cells." (PMID 38730579, 2024). "Studies have revealed that CXCR3+ CD4+ T cells were critical in preventing persistent HPV infection and cancer progression, while CXCR3+ CD4+ Trm cells were irreversibly depleted in patients with advanced HIV disease." (PMID 39902182, 2024). "A significant correlation was found between SCIN expression and CD4+T cells in 20 cancer types, B cells in 21 cancer types, CD8+T cells in 17 cancer types, macrophages in 18 cancer types, neutrophils in 21 cancer types, and dendritic cells in 25 cancer types." (PMID 39108273, 2024). "CD4 was increased in the surrounding stromal leukocyte regions, and CD45, CD20, and CD68 were higher in immune-rich cancer cell islet regions." (PMID 38611634, 2024). "The advantage of using H/K-HELP-DCVAC is that antigen-pulsed activated DCs readily migrate to the TDLN and CD4+ and CD8+ T cells respond to DCs presenting WT-1 and survivin, which are expressed in most cancers, resulting in effective cancer therapy." (PMID 39411614, 2024). "An investigation demonstrated that DCs evoke CD4+ TH2 cells for pancreatic antigens, thereby advancing the transition from pancreatitis to cancer." (PMID 38835055, 2024). "By fusing α-CD3εscFv to our α-LGR5scFv we generated the CL-BiTE which displayed highly specific and potent activation of human CD4+ and CD8+ T cells and effectively induced cancer cell killing in vitro." (PMID 39169164, 2024).
cancer (continued). "When contrasting the utilization of separate T-cell subsets for CAR-T cells, the concurrent application of CD4+ and CD8+ subsets demonstrates synergistic anti-cancer properties." (PMID 39409959, 2024). "CD4+ T cells assist in activating CD8+ T cells, which then transform into effector cells capable of directly destroying cancer cells." (PMID 39479459, 2024). "These factors include older age, lower latest CD4 count, higher latest HIV viral load, and the presence of cancer." (PMID 38630534, 2024). "Collectively, these findings indicate that the distribution patterns of various immune cell markers, including CD3, CD4, CD8, CD20, CD57, CD68, and CD163, hold potential as prognostic indicators for individuals diagnosed with cancer." (PMID 38730579, 2024). "Macrophages, CD4+ T cells, B cells, CD8+ T cells and neutrophils are found in the TME, and involve in the occurrence of cancer." (PMID 38164277, 2024). "The role of CD4+T cells in supporting the effector function of CD8+T cells and innate immunity was described in mouse cancer models as early as 1982." (PMID 39000005, 2024). "They stimulate dendritic cell maturation, promote antigen uptake, and enhance CD4+ T cell levels, leading to increased infiltration of CD8+ T cells in cancer immunotherapy." (PMID 38566199, 2024). "For instance, the NY‐ESO‐1 DNA vaccine, has been shown to elicit strong CD4+ and CD8+ T‐cell responses in cancer patients." (PMID 39275923, 2024). "IL-6 transduction signaling mechanisms activate various pathological pathways, such as JAK/STAT3, Ras/MAPK, and PI3K-PKB/Akt, and regulate CD4+T cell and VEGF levels, leading to cancer, inflammatory diseases, and neurological diseases." (PMID 38645489, 2024). "This study also emphasized the role of BMX in immune cell infiltration, such as B cells, CD4+ T cells, CD8+ T cells, neutrophils, macrophages, and dendritic cells in certain cancers." (PMID 39347140, 2024). "In this cohort, CD55 expressed by CAFs, basal cancer cells, and monocyte/macrophages was predicted to interact with CD97 (ADGRE5) on CD4+ T cells, which promotes Treg development." (PMID 39483921, 2024). "Our findings uncovered an unappreciated paracrine mechanism how cancer cell-derived BCL6 assists cancer cell immune evasion, and highlighted the role of CD4+T cells in HCC immune surveillance." (PMID 38956432, 2024). "The frequency of CD4+ and CD8+ T cell subsets in the blood can differ markedly in cancer patients because of age, the effects of chemotherapy, and thymic function." (PMID 39627220, 2024). "We used the TIMER database to analyze the relationship between GAB2 and the degree of infiltration of B cells, CD4+ T cells, CD8+ T cells, neutrophils, macrophages, and dendritic cells in pan-cancer." (PMID 38995439, 2024). "The median proportions of T cells CD4 memory resting, T cells CD8, Tregs, and macrophages M2 were higher in the primary cancer samples." (PMID 39452125, 2024). "Correlation analysis with immunohistochemistry findings showed that the degrees of CD4 + and CD163 + cell infiltration and IL-6 and MMP-11 expression were correlated with cancer imaging features on PET/CT." (PMID 38627864, 2024). "The densities of nTOB1+CD4+ T cells, cTOB1+CD4+ T cells, nTOB1+CD20+ B cells, and cTOB1+CD20+ B cells were significantly lower in cancer tissues than in paracancerous tissues (P < 0.001, P < 0.001, P < 0.001, and P < 0.001, respectively)." (PMID 38617839, 2024). "T cells (primarily CD4+ T, CD8+ T cells, and CTLs) can identify cancer cells throughout the development of cancer and either directly kill cancer cells by releasing cytotoxins, or they can attack cancer cells by stimulating other immune cells." (PMID 38553639, 2024). "cTOB1/nTOB1 showed relatively diminished expression in CD4+ T cells and CD20+ B cells, both of which showed reduced infiltration in cancer tissues compared to that in paracancerous tissues." (PMID 38617839, 2024).